GPC1 (glypican 1)
Diseases named in the same sentence as GPC1 in open-access papers (continued):
Sharing a sentence is not in itself a finding about the gene and the disease.
glioma (continued). "In gliomas, GPC1 contributes to enhance mitogenic signaling via forming a ternary complex with FGF2 and the FGFR and activating both MAPK/ERK and PI3K/AKT pathways." (PMID 32916872, 2020). "GPC1 (glypican-1) is a member of the heparan sulphate proteo-glycan family and is an important biomarker, found in several types of cancer (breast, pancreatic, and glioma) and involved in angiogenesis and tumor growth." (PMID 31737071, 2019). "In the present study, we found that ANXA2 increased the expression of GPC1 via c-Myc and that the upregulated GPC1 further promoted the c-Myc level, forming a positive feedback loop, which eventually led to enhanced proliferation of glioma cells." (PMID 33712571, 2021). "We subsequently studied the expression of ANXA2 and GPC1 in clinical glioma samples." (PMID 33712571, 2021). "Considering the crosstalk between ANXA2 and GPC1, we further determined whether coexpression of ANXA2 and GPC1 could act as a predictor of glioma prognosis." (PMID 33712571, 2021). "ANXA2 increased the expression of GPC1 via c-Myc and the upregulated GPC1 further promoted the c-Myc level, forming a positive feedback loop, which eventually led to enhanced proliferation of glioma cells." (PMID 33712571, 2021). "All these results indicated that ANXA2 increased the expression of GPC1 via c-Myc and that the upregulated GPC1 further promoted the c-Myc level, forming a positive feedback loop, which eventually led to enhanced proliferation of glioma cells." (PMID 33712571, 2021). "Because our in vitro results confirmed that ANXA2 promoted proliferation by regulating GPC1, we speculated that GPC1 overexpression in glioma may be attributed to the dysregulated expression of ANXA2." (PMID 33712571, 2021). "However, Qiao‘s study showed that moderate GPC-1 overexpression could stimulate glioma blood vessel endothelial cell (EC) growth, but proliferation was inhibited when GPC-1 was either knocked down or overexpressed." (PMID 36313694, 2022). "However, the upstream regulator of GPC1 implicated in the proliferation of glioma cells is not fully understood." (PMID 33712571, 2021). "Finally, we utilized a tissue microarray (TMA) and immunohistochemistry to demonstrate that combined indexes of ANXA2 and GPC1 could improve the evaluation of prognosis in glioma patients." (PMID 33712571, 2021). "SLC47A1, GPC1, CAV1, and SLC18B1 are involved in polyamine transport; however, only CAV1 has been extensively studied in gliomas and is involved in stemness and temozolomide resistance." (PMID 40761256, 2025). "This analysis identified CSPG4, PTPRZ1, and BCAN as the most highly expressed and concordant ECM targets in adult gliomas, while GPC1, CSPG5, and TNR were the top concordant targets in pediatric gliomas." (PMID 40517137, 2025). "For example, GPC1 specifically forms a ternary complex with FGF2 and FGF-receptor 1 to promote cell signaling pathway activation in glioma vessel endothelial cells." (PMID 34957110, 2021). "Then, the relationship between ANXA2 and GPC1 was investigated by scatter plot analysis, revealing a significant positive correlation between the ANXA2 and GPC1 mRNA levels in the glioma samples (Pearson’s correlation, n = 90, r = 0.878, P < 0.001)." (PMID 33712571, 2021). "In vitro studies targeting GPC1 expression by CRISPR/Cas9 or siRNA or treatment with an anti-GPC1 antibody resulted in attenuation of proliferation of cancer cells from bladder carcinoma, glioma and hepatocellular carcinoma patients (T24, U87 and HepG2 cells)." (PMID 36944188, 2023). "Besides, we utilized tissue microarrays (TMAs) and immunohistochemistry to demonstrate that glioma patients with both high expression of ANXA2 and GPC1 tended to have higher rate of tumor recurrence and shorter overall survival (OS)." (PMID 33712571, 2021).
glioma (continued). "Furthermore, univariate and multivariate analyses revealed that in addition to WHO grade and age, the combination of ANXA2 and GPC1 (ANXA2/GPC1) was an independent prognostic factor for TTR (P < 0.001, HR = 3.575, respectively) and OS (P = 0.001, HR = 2.174, respectively) in glioma patients." (PMID 33712571, 2021). "The data indicated that even without the stimulation of FGF-2, the pro-proliferative effect of GPC1 could be present in U118 glioma cells, which contain high levels of endogenous GPC1 (data not shown)." (PMID 33712571, 2021). "Nevertheless, whether GPC1, the key regulator of glioma cellular proliferation, is regulated by ANXA2 has not yet been studied." (PMID 33712571, 2021). "Interestingly, glypican-1 was highly expressed in glioma vasculature, while absent in normal brain ECs." (PMID 23152853, 2012). "In conclusion, the overexpression of ANXA2 promotes proliferation of glioma cells by forming a GPC1/c-Myc positive feedback loop, and ANXA2 together with its downstream target GPC1 could be a potential “combination biomarker” for predicting prognosis of glioma patients." (PMID 33712571, 2021).
esophageal squamous cell carcinoma (17 papers, 2017 to 2024). Esophageal squamous cell carcinoma (ESCC) is a type of esophageal carcinoma (EC) that can affect any part of the esophagus, but is usually located in the upper or middle third. "GPC-1 was found expressed in 98.8% of esophageal squamous cell carcinoma patients’ tumor tissue with higher levels associated with poorer prognosis." (PMID 32782317, 2020). "Heparan sulfate proteoglycan glypican‐1 (GPC1) is a core protein of the GCX that is overexpressed in esophageal squamous cell carcinoma (ESCC) and is involved in the development and progression of cancer cells." (PMID 39300946, 2024). "As previously demonstrated for esophageal squamous cell carcinoma, GPC1 does indeed directly affect β-catenin expression." (PMID 32180897, 2020). "An anti-GPC1 monoclonal antibody has shown potent antitumor activity in esophageal squamous cell carcinoma, whereas a human monoclonal antibody against GPC3, HS20, destroying Wnt3a and GPC3 interaction and subsequent signaling, exhibits elevated antitumor activity in liver cancer." (PMID 32916872, 2020). "This study presents novel findings on the role of glypican‐1 (GPC1) in esophageal squamous cell carcinoma (ESCC)." (PMID 39300946, 2024). "We previously identified glypican-1 (GPC-1) by quantitative proteomics as an antigen for oesophageal squamous cell carcinoma (ESCC)." (PMID 32152502, 2020). "This anti-GPC1 mAb recognized both human and mouse GPC1, and inhibited the growth of GPC1-expressing human esophageal SCC xenografted in immunodeficient mice without any obvious adverse effects." (PMID 32228854, 2020). "Among the 6 known glypicans, glypican-1 (GPC1) has gained significant attention because of its aberrant expression in several types of cancer, including pancreatic, breast, and uterine cervical cancers, as well as esophageal squamous cell carcinoma and cholangiocarcinoma." (PMID 37827841, 2023). "In this study, we evaluated hGPC1 protein expressions by IHC using our anti-GPC1 mAb (clone: 1–12) and found that GPC1 expression was under the detection sensitivity in human normal tissues, whereas human esophageal SCC tissues showed strong and broad expression." (PMID 32228854, 2020).
glioblastoma (17 papers, 2015 to 2025). The most malignant astrocytic tumor (WHO grade IV). "In esophageal squamous cell carcinoma and glioblastomas, GPC1 is also upregulated and associated with tumour angiogenesis and patients’ poor prognosis." (PMID 33494442, 2021). "Further, GPC1 was shown to associate with the dissemination levels of glioblastoma." (PMID 33494442, 2021). "In vitro studies demonstrated that all 89Zr-labeled formats were specifically internalized in GPC-1-expressing glioblastoma cell lines." (PMID 41019666, 2025). "Cellular migration was severely affected, and glypican-1 majorly impacted the affinity towards laminin-binding of glioblastoma U-251 MG cells." (PMID 32180897, 2020). "A consensus clustering algorithm analysis of the 3909 protein groups detected in all the tumor samples identified two stable proteomic subtypes for IDH wild-type GBM: glioblastoma proteome cluster 1 (GPC1, N = 26) and GPC2 (N = 13)." (PMID 32620753, 2020). "This study aimed to investigate how glypican-1 influences the tumoral profile of human glioblastoma using in vitro cell line models." (PMID 32180897, 2020). "Protein expression of GPC-1 has been described in breast, pancreatic, bladder, cervical and oesophageal cancers and glioblastoma." (PMID 33302918, 2020). "Glypican-1 has been previously shown to be overexpressed in human glioblastoma and to be negatively correlated with patient’s survival." (PMID 32180897, 2020). "Recent studies have also showed a down-modulation of Glypican-3 and an up-regulation of Glypican-1 gene expression in glioblastoma." (PMID 26517809, 2015). "Furthermore, high expression of GPC1 has been suggested to predict poor prognosis of glioblastoma in a study examining the expression of GPC1 in 53 patients." (PMID 33712571, 2021). "High GPC-1 expression has been shown to correlate with poor prognosis for certain solid tumours including glioblastoma, pancreatic and oesophageal cancer; thus, Miltuximab® theranostics may have utility in other solid tumours." (PMID 32382920, 2020). "Therefore, we present evidence not only to support facts that glypican-1 is an elementary macromolecule in glioblastoma tumoral microenvironment but also to introduce this proteoglycan as a promising therapeutic target for this lethal tumor." (PMID 32180897, 2020). "In vitro analysis of glioblastoma as an acutely angiogenic tumor type revealed that glioblastoma-derived exosomes contain high levels of miR-221, proteoglycans glypican-1 and syndecan-4 that increase revascularization via enhancing proliferation and formation of endothelial cells and tubules." (PMID 30940145, 2019). "Although GPC1 has received little focus in regard to glioblastoma, Saito & colleagues demonstrated how this molecule influences the lower survival of GBM patients." (PMID 32180897, 2020).
chronic pancreatitis (16 papers, 2017 to 2025). A chronic inflammatory process causing damage and fibrosis of the pancreatic parenchyma. "Furthermore, at the mRNA level, we found that GPC1 was higher in patients with a chronic pancreatitis background and drinking habits, indicating that inflammation‐related risk factors may facilitate the expression of GPC1 in PDAC." (PMID 28440066, 2017). "GPC-1 circulating exosomes (GPC-1 crExos) have been reported to exhibit high specificity and sensitivity (AUC = 1.0) in recognizing healthy individuals and patients with chronic pancreatitis PDAC, superior to CA199 (AUC = 0.739)." (PMID 38254825, 2024). "Glypican-1(GPC1) is highly expressed in PCCs and adjacent fibroblasts, but less expressed in the normal pancreas and in chronic pancreatitis." (PMID 38720811, 2024). "Northern blot analysis showed that mRNA expression of GPC1 was 8-fold higher in cancer tissues than in chronic pancreatitis and normal pancreas tissues." (PMID 36142190, 2022). "Immunohistochemical studies showed that GPC1 was not present in the normal pancreas, that GPC1 was undetectable in most chronic pancreatitis samples, and that GPC1 staining was very weak in adjacent normal tissues." (PMID 36142190, 2022). "For chronic pancreatitis, we observed several cases of PanIN, low-grade, with weak to moderate GPC1 expression (15 of 20 chronic pancreatitis cases)." (PMID 29245923, 2017). "The patients with alcoholic drinking habits, chronic pancreatitis, and poor pathological differentiation tended to express high levels of GPC1 (Mann–Whitney U tests, all of P < 0.05)." (PMID 28440066, 2017). "For instance, a comparative analysis of exosomal GPC1 and miRNA in circulatory exosomes of healthy, chronic pancreatitis, and PDAC participants revealed that exosomal miRNA showed better differentiation of normal, CP, and PDAC patients than GPC1." (PMID 36980662, 2023). "Thus, GPC1 is highly expressed in PDAC and metastatic tissues compared with normal tissues and chronic pancreatitis." (PMID 36142190, 2022). "Most of the chronic pancreatitis cases still lacked GPC1 expression." (PMID 28440066, 2017). "The proteoglycan glypican-1 (GPC1) may be a useful immunotherapeutic target because it is highly expressed on the surface of PDAC cells, whereas it is not expressed or is expressed at very low levels in benign neoplastic lesions, chronic pancreatitis, and normal adult tissues." (PMID 38017492, 2023). "Among the various TAA, one of the possible candidates is glypican-1 (GPC1), which is highly expressed in PDAC tumor tissues and is not expressed or is expressed at very low levels in normal pancreatic tissue and in chronic pancreatitis." (PMID 38017492, 2023). "GPC1 is highly expressed in PDAC tissues at both the mRNA and protein levels, whereas it is absent or very low in normal pancreas and chronic pancreatitis." (PMID 36142190, 2022).
hepatocellular carcinoma (11 papers, 2015 to 2025). A malignant tumor that arises from hepatocytes. "However, little is known about the expression levels and clinical relevance of GPC-1 in pan-cancer, especially its roles in hepatocellular carcinoma (HCC)." (PMID 38982153, 2024). "Recent studies indicate that Glypican 1 (GPC-1) is aberrantly expressed and plays a key role in certain cancers, but little is known in the hepatocellular carcinoma." (PMID 38982153, 2024). "A study in regard to glypican-1 (GPC3), which is a new prognostic factor for early hepatocellular carcinoma (HCC), showed that epitopes selected by technical websites have the ability to bind to T2 cells." (PMID 28509875, 2017).
esophageal cancer (7 papers, 2020 to 2024). A primary or metastatic malignant neoplasm involving the esophagus. "In the present study, we analyzed the association between GPC1 protein levels in plasma and clinicopathological factors as well as prognosis in esophageal cancer patients." (PMID 39300946, 2024). "We also analyzed plasma GPC1 levels in healthy volunteers (n = 60) and esophageal cancer patients (n = 39)." (PMID 39300946, 2024). "In the present study, we measured the concentration of GPC1 protein in the plasma of esophageal cancer patients." (PMID 39300946, 2024). "We measured preoperative plasma GPC1 protein concentrations by ELISA in 69 patients who underwent esophagectomy for advanced esophageal cancer." (PMID 39300946, 2024). "Although the roles of GPC1 expression in ESCC has been reported previously, this study is the first to evaluate the effects of extracellular GPC1 in esophageal cancer." (PMID 39300946, 2024). "We measured the concentration of GPC1 protein in preoperative plasma from advanced esophageal cancer patients and examined its relationships with clinicopathological factors and therapeutic efficacy, and the effects of extracellular GPC1 were investigated." (PMID 39300946, 2024). "Lastly, we showed that extracellular GPC1 protein plays a role in both tumor cell motility and cancer progression, which indicated that it may be a candidate therapeutic target for esophageal cancer." (PMID 39300946, 2024). "GPC1 is upregulated in pancreatic cancer, esophageal cancer, and prostate cancer." (PMID 33302876, 2020). "Therefore, we hypothesize that extracellular GPC1 will be useful not only for an esophageal cancer progression biomarker but also as a therapeutic target for esophageal cancer." (PMID 39300946, 2024). "Thus, plasma GPC1 is a useful biomarker for esophageal cancer progression and may be a potential candidate of therapeutic target." (PMID 39300946, 2024). "Therefore, plasma GPC1 derived from normal endothelial cells of esophageal cancer patients will be lower than that of healthy volunteers, and difference in blood GPC1 concentration between healthy volunteer and esophageal cancer patients may be unclear." (PMID 39300946, 2024). "Furthermore, the effect of extracellular GPC1 protein on esophageal cancer cells was evaluated." (PMID 39300946, 2024). "Furthermore, GPC1-targeted mAb drug conjugates have been developed and have shown great potential for the effective treatment of refractory PDAC and esophageal cancer." (PMID 37827841, 2023). "However, there are no reports which have investigated GPC1 in the plasma of esophageal cancer patients using liquid biopsy." (PMID 39300946, 2024).